CDK12 (cyclin dependent kinase 12)
Diseases named in the same sentence as CDK12 in open-access papers (continued):
Sharing a sentence is not in itself a finding about the gene and the disease.
cancer (continued). "More precise and better-tolerated inhibitors targeting CDK7 and CDK12 are necessary in order to gain a complete understanding of the potential of these kinases as therapeutic targets in GBM, as well as other types of cancer." (PMID 40996961, 2025). "This study revealed that genetic or pharmacologic inactivation of CDK12 and its paralog CDK13 robustly activates stimulator of interferon genes (STING) signaling across multiple cancer types." (PMID 40955658, 2025). "Our findings underscore the urgency of initiating clinical trials to evaluate the combination of CDK12/13 antagonism and ICB therapy as an approach to improve cancer treatment outcomes." (PMID 40955658, 2025). "Significant attention has been paid to the role that transcriptional CDKs play in cancer, including CDK7, CDK8, CDK9, CDK12, and CDK13." (PMID 40361480, 2025). "Selective degradationof cyclin-dependent kinases 12 and 13 (CDK12/13)emerges as a new potential therapeutic approach for triple-negativebreast cancer (TNBC) and other human cancers." (PMID 39388374, 2024). "In 33 cancer types, mast cells, CD4+Th2 T cells, Tregs, and common lymphoid progenitors were positively correlated with CDK12 expression." (PMID 38503865, 2024). "In this study, we introduce YJ9069, a highly specific PROTAC degrader, targeting the CDK12/13/CCNK complex, demonstrating cytotoxicity at nanomolar concentrations across a spectrum of cancers." (PMID 39353441, 2024). "A population-wide examination of TT and LN single cells found that primary cancer overexpresses NOTCH2, NOTCH2NL, KIF5B, and ERBB4 but that metastatic cancer overexpresses CDK12, ERBB2, and CLDN11." (PMID 37322261, 2024). "Collectively, these results show that YJ9069 is a specific PROTAC degrader of CDK12 and CDK13 with potent growth inhibitory effects in subsets of cancer cell lines." (PMID 39353441, 2024). "The overlap between MYC and the known cellular functions of CDK12, as well as the requirement of CDK12 for optimal processing of MYC, collectively indicates CDK12 is a potential therapeutic target for MYC‐dependent cancers." (PMID 36670542, 2023). "SR4835 was used in mouse models in several studies to investigate the role of Cyclin K, CDK12, or CDK13 in cancers." (PMID 37626854, 2023). "THZ531 inhibits both CDK12 and CDK13, and studies have shown that THZ531 reduces Pol II phosphorylation and the proliferation of many types of cancer cells." (PMID 38104154, 2023). "As exemplified by EGFR and RPTOR, these new CDK12/13 target genes function in pathways that are actionable in HGSOC, as clinically approved inhibitors have shown efficacy in other cancer types." (PMID 37202753, 2023). "CDK12 and CDK13 have gained considerable attention as powerful oncogenic targets in the last years, especially for MYC-driven cancers." (PMID 37202753, 2023). "We found that CDK12/13 inhibitors, AU-15506 and AU-16770, are very effective in inhibiting osimertinib-resistant H1975-osiR-NCI1, PC9-osiR-NCI1, and HCC827-osiR-NCI1/2 cancer cell growth in vitro, either alone or in combination with osimertinib." (PMID 37190191, 2023). "Furthermore, metastasis‐associated cellular features including proliferation, survival and cancer stem cells (CSCs) of CRC cells were greatly dependent on transcription of SE‐associated oncogenes (e.g., BCL2L1, CCDC137), which were exceptionally vulnerable to SE interruption by CDK12 inhibition." (PMID 36254394, 2022). "CDK12, a member of the CDK family, has also been shown to play an important role in various human cancers, suggesting that it is a potential biomarker of cancer." (PMID 36338621, 2022). "The previous discovery of the covalent CDK12 inhibitor THZ531 revealed consistently inhibited CDK12 kinase activity and suppressed cancer cell proliferation." (PMID 33628849, 2021).
cancer (continued). "However, in the presence of stable knockout of CDK12 activity, it is likely that a few surviving cancer cells accumulate large genomic aberrations that may ultimately create new oncogenes and generate a highly resistant phenotype, as observed in advanced prostate cancer." (PMID 34092037, 2021). "Suppression of CDK12 or THZ531, CDK12 inhibitor, has been shown to inhibit cell proliferation and induce apoptosis in cancer cells." (PMID 33628849, 2021). "The expression levels of CDK12 and its partner cyclin, cyclin K (CCNK), are unchanged throughout the normal cell cycle but are frequently elevated in proliferating stem cells and cancer cells." (PMID 32451425, 2020). "H&E staining images illustrated that knock-down of CDK12 suppressed the vitality of cancer cells, and IHC analyses showed that CDK12, Ki67, phospho-MEK and phospho-ERK levels were significantly decreased in CDK12 knock-down tumors." (PMID 32483448, 2020). "Given the known roles of CDK12 in cancer, THZ1 was used as a starting point to develop THZ531, a selective CDK12/13 inhibitor." (PMID 32397434, 2020). "Subsequent studies also reported that suppression of CDK12 with either short hairpin RNAs (shRNAs) or THZ531 strongly inhibited cell proliferation and impaired the colony formation in cancer cells." (PMID 32570740, 2020). "Recent evidence has shown that CDK12 plays a unique role among CTD kinases in regulating genome stability and cancer cell drug resistance." (PMID 32451425, 2020). "To confirm the function of CDK12 in tumorigenicity, we inhibited CDK12 mRNA expression in the TPC-1 and KAT-5 cancer cell lines." (PMID 32489449, 2020). "Moreover, functional studies suggest that CDK12-mediated cell cycle and metabolic vulnerabilities and the CDK12-induced neoantigens load might be promising candidates/biomarkers for targeted CDK12-specific cancer therapy." (PMID 34316683, 2020). "The broad pan-cancer HER2 amplicon shared by at least 60% of HER2A tumors spans 532 kb, contains 13 additional genes from CDK12 to PSMD3, and is narrower compared to breast." (PMID 29382369, 2018). "For example, the RNA splicing and processing theme involves 2,009 pSNVs in 652 genes, including 38 known cancer genes such as BRCA1, RBM15, CDK12, CDC73 and TOP1 (FDR p = 1.3e − 06, Fisher's exact test), as well as candidate cancer genes." (PMID 24089029, 2013). "These diverse strategies allow fine-tuned dissection of CDK12/13 biology and offer multiple routes to pharmacologically induce “BRCAness,” enhance PARP-inhibitor sensitivity, and overcome transcriptional therapy resistance across cancer types." (PMID 41491919, 2026). "First, a striking functional dependency on both CCNK and CDK12 is evident across most cancer cell lines, as demonstrated by pan-cancer negative CRISPR scores." (PMID 41491919, 2026). "This review aims to synthesize current knowledge on Cyclin-dependent kinase 12 (CDK12) and Cyclin-dependent kinase 13 (CDK13), two transcriptional kinases with distinct and overlapping roles in gene regulation, genome stability, and cancer biology." (PMID 41491919, 2026). "The key functions of CDK12/13 in promoting transcription and splicing of DDR genes, together with studies reporting their oncogenic roles, make these kinases an ideal target for novel anti-cancer therapies." (PMID 39533070, 2025). "One can speculate that the role of CDK12 and CDK13 in regulating transcription in cancer cell lines is different from that in primary cells such as oocytes." (PMID 40148269, 2025). "CDK12 has not received much attention as a potential cancer treatment, except in cases like triple-receptor negative breast cancer model systems." (PMID 40996961, 2025). "Targeting CDK12 is currently a focus of precision therapy for cancer, and no specific CDK12 inhibitors have yet been clinically available." (PMID 38503865, 2024).
cancer (continued). "Subsequently, the CDK12 expression levels in cancerous and paired normal samples from the GTEx and TCGA databases revealed significant differences from normal tissue in 25 cancers, excluding those without normal sample comparison." (PMID 38503865, 2024). "The results confirmed the strong anti-cancer activity of cyclin-dependent kinase 12 and 13 (CDK12/13) inhibitors and the synergistic effect of THZ531 and pathway inhibitors (EGFR, RPTOR, ATRIP) regulated by cancer-related genes on the activity of HGSOC organoids." (PMID 38989138, 2024). "We investigated the correlation between CDK12 expression and MSI in 33 types of cancer." (PMID 38503865, 2024). "The development of CDK12/13 inhibitors, such as the irreversible covalent inhibitor THZ53120,32,33 and the noncovalent inhibitor SR-4835,16 has shown promise in inducing synthetic lethality in multiple cancer types." (PMID 39353441, 2024). "Patients without concomitant CDK12 amplification in HER2‐positive NST carcinomas had better prognosis." (PMID 38335502, 2024). "CDK12 and CDK13 are emerging as suitable targets in human cancers, including HGSOC." (PMID 37202753, 2023). "Furthermore, since CDK12 predominantly regulates the expression of DDR-related genes, CDK12 inhibitors in combination with PARP inhibitors induce synthetic lethality in cancer cells." (PMID 37342192, 2023). "In contrast to CDK12, current evidence indicates that the role of P-TEFb in cancer is chiefly, if not exclusively, oncogenic." (PMID 37811895, 2023). "However, during the past two decades, increased efforts have been made to understand the functions of the catalytic subunits CDK12 and CDK13 in cancer biology." (PMID 37626854, 2023). "For GP5, CDK12 inactivation and gains of AKT1, GSK3B, PIK3CA, CCND1, and MDM2 were identified as the top truncal druggable targets that would be most likely to obtain a durable response due to their presence in all cancer cells." (PMID 37828555, 2023). "The other two amplifications in CDK12 and MAPK1, respectively, were considered tumorigenic in other cancer types, suggesting that may also be tumorigenic in BC." (PMID 37345205, 2023). "However, throughout this study we showed differences between CDK12 and CDK13 in terms of their effects on cancer cell fitness and their genetic co-dependencies." (PMID 36577800, 2022). "In our study, we report the co-occurrence of truncating mutations in ATM, CDK12, PTEN or ATR is present in 80% of MSS CRC with TMB-H and absent from TMB-L MSS cancers." (PMID 35740599, 2022). "Although our results showed CDK12 essentiality is not dependent on cancer lineage, further work is needed to determine genetic and/or molecular features associated with sensitivity to loss of CDK12 activity." (PMID 36577800, 2022). "While both CDK12 and CDK13 are bound to cyclin K and target the CTD in vivo, most studies have focused on CDK12’s function, mainly because it has emerged as an important player in human cancers." (PMID 34146121, 2021).
cancer (continued). "Following large-scale cancer sequence analysis, many other HRD-related genes (CDK12, ATM, PALB2) were commonly found in mCRPC, and these non-BRCA DNA repair genes could be used as alternative biomarkers to predict the sensitivity of PARP inhibitors." (PMID 34975480, 2021). "Therefore, the synthetic lethal relationship based on PARP1 inhibition could be applied to CDK12 mutants, similar to its application to BRCA1 mutants, and CDK12 inhibition might provide a rationale for the use of combination therapy with a PARP inhibitor in CDK12 mutation-related cancers." (PMID 32451425, 2020). "The animal metastasis model also verified that the lack of CDK12 inhibited cancer metastasis, and the metastatic lung nodule loads were lower than those in the sh-CTR group." (PMID 32489449, 2020). "Among these proteins, cyclin-dependent kinase 12 (CDK12) and core-binding factor subunit beta (CBFB) were overexpressed in tumors, which were consistent with their oncogenic role in certain types of cancer." (PMID 33287876, 2020). "Given the recent FDA-approval of larotrectinib for NTRK-altered cancers regardless of histologic type, we envision a similar mode of clinical exploration for CDK12-altered tumors." (PMID 31360735, 2019). "Considering that Cdk12 regulates the expression of several cancer-related genes, such as BRCA1, it comes as no surprise that the dysregulation of Cdk12 has been identified in several cancers." (PMID 22512864, 2012). "Our findings suggest that CDK12/13 antagonists activate STING signaling and may be leveraged to overcome resistance to immunotherapies, particularly ICB, addressing a critical clinical challenge in cancer treatment." (PMID 40955658, 2025). "Therefore, CDK12 amplification is an extremely rare event in cancer, whereas CDK12 amplification is not infrequent in ERBB2‐amplified ILBC." (PMID 38335502, 2024). "In addition to CDK12, CDK7 inhibitor sensitizes DDR-proficient cancer cells to PARP inhibitor." (PMID 37342192, 2023). "However, CDK12 inhibition may downregulate the expression of FGFR1 and other FGF receptors, potentially inhibiting the signaling pathways that promote cancer cell growth and survival." (PMID 37190191, 2023). "GO analysis of the sensitive genes (reduced ≥1.5‐fold change with SR‐4835 treatment or CDK12 depletion) was enriched in processes of transcriptional regulation, DNA damage, stem cell division, apoptosis, cell proliferation and cell migration in CRC cells, which are essential for cancer metastasis." (PMID 36254394, 2022). "These irreversible inhibitors exhibited prominent anti-cancer phenotypes in cancer cells owing to their highly selective, strong, persistent suppression of CDK12/13, but their in vivo activity could not be evaluated due to their poor stability in vivo." (PMID 36145262, 2022). "Immunotherapy-based approaches have enriched the therapeutical opportunities of many cancer types, improving patient survival; however, to date, in advanced PCa patients, it has no established role outside of retrospective small series data on dMMR/MSI high and CDK12 patients." (PMID 35267553, 2022). "A similar pan‐cancer analysis, which lacked access to detailed clinical data, demonstrated that the prevalence of CDK12 genomic alterations was 1.1% across all cancer types, with mutations most frequently seen in prostate, gastrointestinal, and gynecologic malignancies." (PMID 34898046, 2022). "Thus, dual targeting of CDK12 as both a transcriptional coactivator and a DDR regulator could be very beneficial in identifying a promising therapeutic strategy for these cancer types." (PMID 33805800, 2021). "Positive correlation of CDK12 high expression with Lauren's classification, especially with high number of metastatic lymph nodes suggested that the functions of CDK12 might not be limited to maintain genomic stability of cancer cells." (PMID 31523177, 2019).
cancer (continued). "Whereas CDK19 and CDK20 are not essential in any of the cancer cell lines tested, there is a minor proportion of cell lines in which CDK8 (~ 3%), CDK10 (~ 1%), CDK12 (~ 27%) and CDK13 (~ 3%) are essential." (PMID 36577800, 2022).
adenocarcinoma (4 papers, 2021 to 2025). A common cancer characterized by the presence of malignant glandular cells. "Elevated levels of CDK12 and CDK13, which form complexes with CCNK, were also associated with worse OS outcomes in patients with adenocarcinoma." (PMID 40075638, 2025). "In our initial studies identifying CDK12 mRNA expression to be negatively correlated with the PD-L1v4/PD-L1v1 mRNA ratio, we examined NSCLC cell lines of adenocarcinoma origin." (PMID 38132164, 2023).
hematologic malignancies (1 paper, 2025). "CDK12 has been proposed as a functionally relevant, potential biomarker in solid cancers, but its role in hematologic malignancies has not been extensively studied." (PMID 40389480, 2025).
kidney (1 paper, 2024). "Taking together, these data indicated that knockdown of CDK12 in TECs accelerates kidney damage and functional decline." (PMID 38481813, 2024).
neurodegenerative disease (1 paper, 2025). A disorder of the central nervous system characterized by gradual and progressive loss of neural tissue and neurologic function. "Moreover, since neither study focused on brain, a direct evaluation of the role and impact of altered CDK12/13 function in brain aging and/or neurodegenerative diseases would be extremely interesting." (PMID 39533070, 2025).
CDK12 also shares sentences with these, for which no sentence is quoted: biliary tract cancer (2 papers); cholangiocarcinoma (2); endometrioid carcinoma of the ovary (2); esophageal cancer (2); lymph node metastasis (2); bone metastasis (1); chronic kidney disease (1); chronic myeloid leukemia (1); colon adenocarcinoma (1); colorectal tumors (1); diabetes (1); ductal breast carcinoma in situ (1); familial cancers (1); female reproductive cancers (1); head and neck cancer (1); head and neck squamous cell carcinoma (1); Holt-Oram syndrome (1); hyperhomocysteinemia (1); Hypertension (1); intraductal cribriform breast adenocarcinoma (1); invasive ductal breast carcinoma (1); kidney cancer (1); liver cancer (1); lymphoma (1); mesothelioma (1); nervous system diseases (1); non-small cell lung carcinoma (1); oesophageal cancer (1); ovarian serous cystadenocarcinoma (1); paraganglioma (1).
A further 9 diseases each share a sentence with CDK12 in 1 paper.